MMP2 (matrix metallopeptidase 2)
Diseases named in the same sentence as MMP2 in open-access papers (continued):
Sharing a sentence is not in itself a finding about the gene and the disease.
tumor (continued). "Among all the MMP proteins identified so far, MMP-2 and MMP-9 are considered to be the most crucial members involved in tumor migration and invasion." (PMID 34149918, 2021). "Especially, increased expression and activity of MMP-2 and MMP-9 subtypes in tumors are known to be related to the degradation of basement membranes—an essential step in tumor invasion and in enhancing angiogenesis." (PMID 33498762, 2021). "Mice in this group showed similar tumor sizes and weights, and according expression level of epithelial–mesenchymal transition molecules, including vimentin, MMP9, MMP2, AXIN-1, N-cadherin, and E-cadherin, compared to mice in the control group." (PMID 33608495, 2021). "Higher expression levels were found in the tumor tissues than in the corresponding normal tissues, except for EMILIN1 and MMP2." (PMID 35071018, 2021). "Following uptake, the MMP-2 degradable peptide is degraded by overexpressed MMP-2 in the tumor tissue, resulting in the release of gelonin-LMWP and endocytosis by the tumor cells, facilitated by the cell penetrating peptide." (PMID 34361141, 2021). "The role of MMP-2 and -9, and their tissue inhibitor, TIMP-2, have been investigated in several human neoplasms for their supposed role in cancer invasiveness." (PMID 35010907, 2021). "Similar results were found on MMP-2 where CTX also inhibited MMP-2 expression by 37 and 41% under basal and tumor stimuli, respectively." (PMID 34421610, 2021). "MMP-2 is an invasion-related protein; thus, we detected the expression of MMP-2 in order to investigate the effects of LMWF and 5-FU on the migration of tumor cells." (PMID 34360807, 2021). "In HCC, BK-BDKRB2 promotes the migration and invasion of tumor cells through transient receptor potential cation channel subfamily M member 7 (TRPM7) and matrix metalloproteinase-2 (MMP2)." (PMID 33686021, 2021). "This study's western blot results showed that the recombinant Hespintor group and the Sorafenib group displayed significantly inhibited expressions of MMP2 and MMP9 in the nude mice's tumor tissues." (PMID 33391431, 2021). "HIF-1α/NRP1 signaling can subsequently result in activation of MMP2, Vimentin, and VE-cadherin and thus promote EMT and VM, which ultimately contribute to tumor progression in LUAD." (PMID 33850110, 2021). "MMP-2 and MMP-9 promote the degradation of basement membrane and lead to tumor cell invasion and metastasis." (PMID 35002708, 2021). "Unfortunately, we found no studies of MMP expression in metastatic cell lines nor metastasis in canine patients with OSA despite clear evidence of correlation between MMP-2 and MMP-9 with tumor malignancy." (PMID 33807419, 2021). "The proteins of the cluster were regulated by MMP-2 perturbation and exhibited significantly increased expressions in tissue and plasma as disease progressed from TNM (Tumor, Node, and Metastasis) stage I to II." (PMID 34429501, 2021). "Further, matrix metalloproteinases (MMP2, MMP9), which promote tumor invasion and metastasis, are significantly related to a poor tumor prognosis (pancreatic cancer)." (PMID 34381726, 2021). "Scolopendra is also known to induce the downregulation of matrix metallopeptidase-2 (MMP-2) and -9 in tumor cells, suppress the migration and invasion of tumor cells, and inhibit cell proliferation." (PMID 33673020, 2021). "For example, it can promote cancer cell metastasis by upregulating matrix metalloproteinase-2 (MMP2), MMP9, N-cadherin, and vimentin and can promote tumor cell growth by upregulating β-catenin expression." (PMID 33731686, 2021). "Conversely, expression of MMP2 and MMP11 was found to be reduced in cases with advanced tumor stages (T3–T4) and nodal metastasis (N+)." (PMID 33578082, 2021).
tumor (continued). "Celecoxib in combination with IFNγ reduced the expression of MMP-2, MMP-9, and VEGF-A in tumor and decreased MVD, mediated by the increased amount of CD68+iNOS+ M1 macrophages and by decreased amount of CD68+Arg1+ M2 macrophages in mouse model of LLC." (PMID 34209679, 2021). "MMP2 and MMP7 belong to the family of zinc-dependent endopeptidases, which play a fundamental role in tumor invasion and metastasis." (PMID 33833997, 2021). "Another study investigated the tumor-suppressive mechanisms of ACE2 via angiogenesis and tumor invasion, and found these to be mediated by regulation of MMP-2, MMP-9, and VEGFa." (PMID 33513805, 2021). "Histological analysis showed reduced levels of phosphorylated PI3K and AKT, and decreased levels of MMP-2 in CX3CR1-KD groups than those in control groups, indicating downregulation of the aggressive propensity of tumor cells conferred by CX3CR1-KD treatments." (PMID 33754027, 2021). "MMP2 degrades ECM components of the basement membrane and facilitates tumor invasion while TIMP2 regulates MMP2 activity." (PMID 33995488, 2021). "In the present study, we demonstrated that LMWF enhanced the suppressive effects of 5-FU on tumor cell migration in HCT116 and Caco-2 cells through the c-MET/MMP-2 signaling pathway." (PMID 34360807, 2021). "cancer cell invasion, including ADAMs (as reviewed above), and interestingly, ADAM12, and MMP2 and 9 are all upregulated by TGF-β1 signaling in tumor metastasis." (PMID 33946495, 2021). "The accelerated growth of Mmp2-OE tumors observed in WT recipients was lost in DKO recipients, and tumor weights were similar." (PMID 34032639, 2021). "TGF-β2 expressed by TAMs induces MMP-2 expression and blocks the tissue-inhibitor metalloproteinases 2 (TIMP-2), promoting tumor invasion." (PMID 33766119, 2021). "MMP-2 and MMP-9 are crucial enzymes in the process of tumor metastasis derived from ECM degradation." (PMID 34769276, 2021). "MMP-2 and MMP-9 are members of the matrix metalloproteinase family that can decompose ECM and induce tumor metastasis." (PMID 34612136, 2021). "Matrix metalloproteinase-2 (MMP-2) and matrix metalloproteinase-9 (MMP-9) degrade the extracellular matrix and basement membrane, correlated with tumor invasion and metastasis." (PMID 34065478, 2021). "Meanwhile, down-regulating the expression of MMP2, MMP9 aand MMP13 can reduce tumor cell growth, proliferation and metastasis." (PMID 34820358, 2021). "The tumor microenvironment is rich in stromal cells, such as fibroblasts, and those cells can be re-programmed due to the endocytosis of tumor-derived extracellular vesicles containing TGF-B1, TGF-B2, IL-6, MMP-2, and MMP-9." (PMID 34898576, 2021). "The study outcomes demonstrated that the covalent connection of iRGD via MMP-2 sensitive bonds improves the aggregation and internalization of DOX into tumor cell monolayers and spheroids." (PMID 34575464, 2021). "MMP-2 and MMP-9 are also known to stimulate tumor angiogenesis and EMT through partial proteolysis of the ECM 53-57." (PMID 34326691, 2021). "To determine if MMP2 is produced in B16 tumors in vivo, we sorted CD45+, YFP+ tumor, and YFP– stromal cells from tumors and evaluated gene expression by reverse transcription PCR (RT-PCR)." (PMID 34032639, 2021). "Among these MMPs, MMP-2 and MMP-9 are zinc-containing gelatinases that have been shown to induce tumor progression by promoting cell invasion and metastasis." (PMID 34769032, 2021). "Upregulated expression of growth factors such as IGF1, FGF7, proteases such as MMP2, ECM constituents such as SPP1 also known as osteopontin and chemokine such as CXCL12 may indicate the presence of cancer-associated fibroblasts (CAFs) within the tumor microenvironment." (PMID 34946170, 2021). "Previous studies have reported the role of matrix metalloproteinase-2 (MMP-2) and MMP-9 in cancer development, including tumor cell growth, migration, invasion, and metastasis, and particularly so in HCC." (PMID 34048194, 2021).
tumor (continued). "To evaluate the functional role of MMP-2 in CRC, we next investigated the effect of MMP-2 on migration ability of tumor in vitro cancer cell line." (PMID 34429501, 2021). "Additional cytotoxicity studies confirmed the sensitivity of mCPP–DOX to MMP-2/9-rich tumor cells, with the IC50 value for the masked conjugate being two times lower in MMP-2/9-rich HT-1080 cells than in MMPs-depleted MCF-7 cells." (PMID 33805680, 2021). "The αVβ3-SDC-1 interaction is likely necessary for FAK activation and the subsequent upregulation of MMP-2 and MMP-9, important steps in tumor metastasis." (PMID 35118073, 2021). "CX3CR1-KD or/and LFA-1-KD treatments also downregulated the aggressive propensity of tumor cells, as evidenced by reduced levels of phosphorylated PI3K and AKT, and decreased levels of MMP-2, compared with controls." (PMID 33754027, 2021). "Related studies have proven that MMP-2 and MMP-9 exist downstream of STAT3 and play an important role in tumours." (PMID 34222329, 2021). "The adhesion of tumor cells to the peritoneum is promoted by activated MAFs via enhanced β2-integrin-dependent tumor cell-MAF interactions rather than exposure of the underlying matrix, which may also be mediated by TGF-β1, hepatocyte growth factor (HGF) and MMP2." (PMID 34112258, 2021). "Exosomes containing MALAT1 are released into the tumor microenvironment, inhibiting and depleting YAP1, activating ERK1/2 signal transduction, and enhancing the expression of MMP2 and MMP9, thereby promoting tumor invasion and metastasis." (PMID 35145971, 2021). "miR-1258 played an inhibitory role in the progression of GBM and functioned as a tumor suppressor by down-regulating E2F1 expression and attenuated E2F1-mediated downstream gene PCNA and MMP2 transcriptions." (PMID 34079762, 2021). "The CHI3L1, MMP2, and IL8 form a triad based on the correlation matrix, which seems to play a central role in tumor local and distal development." (PMID 33846436, 2021). "Secreted proteases, such as MMP-2, MMP-9 promote tumor cell invasion and metastasis by digest the ECM and cell adhesion proteins." (PMID 34094948, 2021). "The imbalance of MMP-2 and its inhibitors TIMP-1 contribute to tumor invasion and metastasis, and tumor progression." (PMID 35201460, 2021). "Western blotting of nude mouse tumor tissues showed that TPL not only inhibited tumor growth, but also reduced the expression of MMP9, MMP2, VEGF, p-PI3K, p-AKT, and p-p65 protein." (PMID 34381726, 2021). "In this study, reduced MMP-2 and MMP-9 expression was found in SCARA5-upregulated group which indicated that MMP-2 and MMP-9-mediated degradation of the extracellular matrix was involved in the tumor suppressive function of SCARA5." (PMID 33758617, 2021). "Matrix‐metalloproteinases (MMPs) (MMP2 and MMP9), closely related to the tumor cell metastasis, were downregulated by EZH2 knockdown." (PMID 31855281, 2020). "CCL3 contributes to tumor progression and poor prognosis in ESCC patients by binding CCR5 on ESCC cells, activating PI3K/Akt and MEK/ERK pathways, upregulating MMP-2 and VEGF-A expression, and promoting cell migration, invasion, and angiogenesis." (PMID 32457351, 2020). "In summary, our findings revealed that downregulation of MMP-2/MMP-9 induces the apoptosis and impairs the viability, migration, and invasion of RB tumor cells, providing a potential MMP target therapy in RB patients." (PMID 32509341, 2020). "The protein expression of N‐cadherin, vimentin, MMP‐2 and MMP‐9 was profoundly elevated in tumours of nude mice injected with oe‐HAND2‐AS1 + sh‐E2F4 and oe‐HAND2‐AS1 + oe‐C16orf74 (P < .05)." (PMID 32314545, 2020). "Once MMP2 cleaves the carrier apart, the chemotherapeutic, doxorubicin, and the PTT agent, palladium nanoparticles, localize within the tumor, resulting in ICD." (PMID 33260534, 2020).
tumor (continued). "Although further examination is needed, it is supposed that the environmental MMP-2/9 level which would be drastically elevated through inflammatory activation of macrophages might be one of the key events for adding aggressive metastatic phenotypes on tumor cells." (PMID 33362799, 2020). "The pro-tumor microenvironment of GBM is supported by the expression of MMPs by TAM, including MMP-2 and MMP-9, which are involved in tumor growth by having an impact on angiogenesis, apoptosis and cell proliferation." (PMID 32765498, 2020). "AURKA overexpression was also suggested to increase the expression of MMP-2, MMP-7, MMP-9, leading to tumor metastasis by degrading extracellular matrix proteins." (PMID 33245732, 2020). "HA-Psi-DOX has significantly toxic to B16F10 cells with high expression of MMP-2 and leads to the “ICD” process, ultimately eliciting an anti-tumor immune response." (PMID 32408880, 2020). "Indeed, an imbalance between MMP-2 and TIMPs might contribute to tumor progression." (PMID 32960785, 2020). "We also detected uniquely in C3N-02671 tumor tissue two protHLAIp TAAs (CCND1 and PXDNL) and five protHLAIIp TAAs (MMP2 and CEACAM5)." (PMID 32157095, 2020). "MMP-2 and MMP-13 were shown to aid the cleavage of the pro domain in pro-MMP-9, which was shown to affect tumor invasion and metastasis by promoting cell migration." (PMID 32466129, 2020). "Among the various MMP family members, the gelatin-degrading enzymes MMP-2 and MMP-9 are considered the tumor-invasive components as their expression levels are often up-regulated in advanced stages of cancer." (PMID 32984054, 2020). "The protein levels of VEGF, MMP9, MMP2 and LOX increased in the sera of CT26‐P2X7R tumour‐bearing mice compared with those of CT26‐Con mice." (PMID 32735377, 2020). "One of the inherent characteristics of MSCs is the ability to implant in tumor tissue that is dependent on multiple cytokine receptors such CXCR4 and matrix metalloproteinase-2 (MMP-2)." (PMID 32370750, 2020). "Expression levels of MMP-2 and MMP-9, major metalloproteinase proteins, produced by GBM cells during tumor invasion was observed following ATX incubation for 24 h by immunoblotting and gelatin zymography, respectively." (PMID 32711429, 2020). "It should be noted that increased MMP-2 and MMP-9, sometimes expressed by BMDCs, support epithelial-to-mesenchymal transition of tumor cells, allowing them to metastasize." (PMID 33276524, 2020). "In this study, the expression levels of MMP‐2 and MMP‐9 in transplanted tumor tissues were significantly decreased during the 3‐7 days of low‐dose apatinib treatment compared with those in other groups (P < .05)." (PMID 32073228, 2020). "Matrine significantly attenuates tumor invasion, activation of MMP-9/MMP-2, Akt phosphorylation, DNA binding activity, nuclear factor-κB expression and mRNA levels of MMP-9, MMP2, EGF, and VEGFR1 in MDA-MB-231 cells." (PMID 33520928, 2020). "Various EMT inducing proteins such as MMP-2, vimentin, snail, slug, N-cadherin and CD44 were analyzed in C4-2 and WT-SPOP tumor lysate." (PMID 33158056, 2020). "According to another study, EGCG decreased MMP-2 expression through JNK signaling and inhibited MMP-7, MMP-9, and MMP-12 in tumor tissues." (PMID 33113766, 2020). "In contrast, expression levels of both MMP2 and MMP9 were significantly higher in tumours excised from the aspirin-treated mice." (PMID 32246008, 2020). "The formation of the invadopodia that promotes the degradation of ECM by the presentation of MMP-14 and secretion of MMP-2 and MMP-9 is a fundamental event during tumor cell invasion." (PMID 33321819, 2020). "DDR1-IN-1 decreased total MMP2 and total MMP9 (mainly detected as pro-MMPs and active MMPs) secretion by basal HSCs and tumor-activated-HSCs." (PMID 33110221, 2020).
tumor (continued). "Several studies have indicated that EGCG appeared to be an inhibitor of cancer cell metastasis via an increase in the expression of E-cadherin and inhibition of the expression of N-cadherin, Zeb-1, MMP-2, and MMP-7 in tumor tissues." (PMID 33113766, 2020). "MMP-2 reshapes ECM by degrading type IV and V collagen, promotes tumor neovascularization and helps tumor invasion and expansion." (PMID 33511267, 2020). "MMP-2 and MMP-9 are essential for tumor dissemination, because in addition to playing an important role in the development of invasive processes, they degrade the components of basement membranes, like type IV collagen." (PMID 32813775, 2020). "Knocking down HMGN5 decreased the expression of Bcl-2, Cyclin D1, MMP-2, and MMP-9 and increased the expression of Bax and p21 which is related to the malignant phenotype of tumor proliferation, migration, and invasion." (PMID 32596388, 2020). "According to the available data, MMP-2 and MMP-7 are among the most important metalloproteinases in the pathogenesis of tumor formation." (PMID 32751899, 2020). "Studies have shown that MMPs, including MMP-2 and MMP-9, are highly expressed in various tumor cells." (PMID 32259133, 2020). "Both MMP-2 and MMP-9 play important roles in tumor invasion, degrading the matrix and activating latent TGF-β present in the extracellular space." (PMID 32948029, 2020). "A study has shown that membrane type 1 (MT1) MMP is enhanced in TAM, which in turn, activates MMP-2 in GBM, via microglial cells, thus increasing tumor invasion." (PMID 32765498, 2020). "It has been shown that elevated expression of MMP2 and MMP9 is positively correlated with tumor progression, metastasis, and poor prognosis." (PMID 32194780, 2020). "According to experimental evidence, EGF has been known to improve cell motility and invasiveness by MMP-2 activation, results in cancer cells enable cross several ECM barriers during tumor metastasis." (PMID 32376896, 2020). "As an MMP superfamily member, MMP2 and 9 can degrade the proteins of the ECM of cancer cells, and they can also promote metastatic tumor cells to penetrate the basal membrane, leading to invasion and metastasis." (PMID 32090682, 2020). "EMT and MMPs are critical for the metastasis of tumour cells; thus, we examined the expression levels of EMT and MMPs markers, such as E-cadherin, vimentin, N-cadherin, MMP2 and MMP9, to explore their correlation with VEGF." (PMID 33193893, 2020). "MMP-2 cleavage and GSH reduction in the tumor microenvironment promoted the degradation of P-NT-aPD1 hydrogel." (PMID 34123123, 2020). "The active form of MMP-2 co-localizes with a pro-form of MMP-9 in various types of cancer, being able to activate it, consequently increasing tumor malignancy." (PMID 33308217, 2020). "Matrix metalloproteinases, particularly MMP‐2 and MMP‐9, are crucial molecules in tumor development, progression, and metastasis." (PMID 32180962, 2020). "CF27 is responsive to MMP-2 and GSH in the tumor microenvironment, Significantly, CF27 contained a peptide sequence for blocking the PD-L1 immunosuppressive signal." (PMID 34123123, 2020). "These exosomes contain various miRNAs, such as, miR-21-5p, miR-139-5p, and miR-100-5p, which control the expression of a panel of MMPs proteins (e.g. MMP2, MMP9, and MMP13) and promote tumor invasion." (PMID 32426106, 2020). "Differential frequency in the expression of MMP-2 and MMP-9 was observed in epithelial and stromal compartments considering the total of tumor samples: 85 and 56% in epithelium and 65 and 16% in stroma, respectively." (PMID 32718331, 2020). "In the same model, thujone also inhibited in vitro secretion of MMP-2 and MMP-9 and the adhesion of tumor cells to the collagen-coated plate, as well as cell invasion and migration." (PMID 32948083, 2020). "Some of MMPs including matrix metalloproteinase 2(MMP-2) and matrix metalloproteinase 9(MMP-9) have significant roles in different stages of tumor progression." (PMID 32582823, 2020).